EEF1D (eukaryotic translation elongation factor 1 delta)
Diseases named in the same sentence as EEF1D in open-access papers (continued):
Sharing a sentence is not in itself a finding about the gene and the disease.
intellectual disabilities (2 papers, 2018 to 2020). "eEF1BδL has been implicated in neurodevelopmental disorders, as EEF1D mutations were identified in severe intellectual disabilities by two independent groups." (PMID 33521052, 2020). "Concerning its physiological roles in humans, EEF1D encodes several proteins, and mutations in this gene have been found in patients with severe intellectual disability and revealed to be related to neurodevelopmental disorders." (PMID 33521052, 2020). "It has been reported that the long isoform of the human EEF1D gene (NM_001130053.1) is a candidate gene leading to neurodevelopmental disorders, such as intellectual disabilities." (PMID 30333725, 2018).
Parkinson’s (2 papers, 2015 to 2023). "Furthermore, rare variants in EEF1D gene were found in late-onset familial Parkinson’s diseases, supporting a possible correlation between EEF1D and the pathogenesis of this disease." (PMID 25686034, 2015).
autoimmune disease (1 paper, 2023). A disorder resulting from loss of function or tissue destruction of an organ or multiple organs, arising from humoral or cellular immune responses of the individual to their own tissue constituents. "Fifteen systematic autoimmune disease patients without neurological manifestations and 30 healthy donors were enrolled for testing for anti-EEF1D autoantibodies, and none of them were positive for recombinant EEF1D CBA." (PMID 38332912, 2023).
cerebellar ataxia (1 paper, 2023). A neurological syndrome characterized by clumsy and uncoordinated movement of the limbs, trunk, and cranial muscles. "The similar clinical manifestations in both patients, with cerebellar ataxia as the main complaint, inflammation of CSF, and effectiveness of immunotherapy, suggest that anti-EEF1D autoantibodies can potentially be used as biomarkers in ACA." (PMID 38332912, 2023).
clear cell carcinoma (1 paper, 2018). "For EEF1D, two analyses of Cutcliffe’s dataset showed higher mRNA levels in renal Welms tumor and clear cell carcinoma." (PMID 29342219, 2018). "However, a single analysis from Gumz dataset showed a lower EEF1D transcript level in clear cell carcinoma." (PMID 29342219, 2018).
colorectal carcinoma (1 paper, 2018). A malignant epithelial neoplasm that arises from the colon or rectum and invades through the muscularis mucosa into the submucosa. "However, a single unique analysis of Hong’s dataset showed that EEF1D was significantly upregulated in colorectal carcinoma." (PMID 29342219, 2018).
gastrointestinal carcinomas (1 paper, 2006). "The overexpression of EEF1D has been associated with advanced tumor stage in gastrointestinal carcinomas and EEF1D reportedly displays oncogenic properties in vitro." (PMID 16968546, 2006).
HIV-1 infection (1 paper, 2020). The type species of lentivirus and the etiologic agent of acquired immunodeficiency syndrome (AIDS). "During human immunodeficiency virus 1 (HIV-1) infection, EEF1D interacted with HIV-1 transcription protein, resulting in the inhibition of the translation of host cell proteins but in an increase in the translation of viral proteins." (PMID 33255903, 2020).
invasive breast carcinoma (1 paper, 2018). A carcinoma that infiltrates the breast parenchyma. "In a single analysis of Finak’s dataset, both EEF1D and EEF2 mRNA levels were significantly reduced in invasive breast carcinoma, compared to normal tissue." (PMID 29342219, 2018).
kidney clear cell carcinoma (1 paper, 2018). "As per TCGA analysis, expression levels of EEF1A1, EEF1B2, EEF1G, EEF1D and EEF2 were significantly upregulated in kidney clear cell carcinoma while that of EEF1E1 was downregulated." (PMID 29342219, 2018).
lung carcinoid tumor (1 paper, 2018). A neuroendocrine neoplasm that arises from the lung. "On the other hand, EEF1D transcript levels were reduced in lung carcinoid tumor in Bhattacharjee’s dataset." (PMID 29342219, 2018).
microphthalmia (1 paper, 2023). Congenital or developmental anomaly in which the eyeballs are abnormally small. "A similar search of DR17 using the term microphthalmia resulted in 22 genes significant for the small eyes phenotype: Aldh1a3, Aff4, Bmp4, Cdk4, Cox6b1, Cxcr4, Dync1li1, Eef1d, Fgd1, Gne, Grh12, Mab21l2, Maf, Med13l, Mllt10, Mthfd2, Pex6, Phgdh, Ssr1, Stim1, Tdo2, and Vps26c." (PMID 36737727, 2023).
ovarian carcinoma (1 paper, 2022). A malignant neoplasm originating from the surface ovarian epithelium. "In the current study, a loss-of-function EEF1D model in human ovarian cancer cell lines was created and its functions in DDP resistance were evaluated." (PMID 35672728, 2022). "The underlying mechanism of reversing ovarian cancer resistance by silencing the expression of EEF1D needs further experimental confirmation." (PMID 35672728, 2022). "To further understand the mechanism of EEF1D affecting human ovarian cancer cell resistance, we performed OPTN knockdown of the DDP-resistant cell line SKOV3/DDP by transient lentiviral infection and found that OPTN KD reversed the effect of EEF1D." (PMID 35672728, 2022). "Using an Annexin V-FITC and PI double-staining method, EEF1D KD and KO were shown to promote the apoptosis of human ovarian cancer cell lines induced by DDP in vitro (P < 0.01)." (PMID 35672728, 2022). "In the present study, EEF1D expression was successfully reduced or removed in human ovarian cancer cells SKOV3 and SKOV3/DDP using gene KO and KD methods." (PMID 35672728, 2022). "We successfully constructed human ovarian cancer cell model knocked down and out EEF1D gene with stable passage, and established an animal model of xenograft mice in human ovarian cancer cell SKOV3/DDP." (PMID 35672728, 2022). "This study firstly demonstrates that EEF1D/PI3K/OPTN/Akt is a novel chemotherapy resistant pathway of ovarian cancer, which partially addresses the molecular mechanism of ovarian cancer chemotherapy-resistance." (PMID 35672728, 2022). "The reducing or removing EEF1D gene expression could significantly increase the sensitivity of human ovarian cancer cells to DDP both in vitro and in vivo." (PMID 35672728, 2022). "The results show that reducing or removing EEF1D gene expression significantly increased the sensitivity of human ovarian cancer cells to DDP in inhibiting viability and inducing apoptosis in vitro and in vivo, and also boosted DDP to inhibit xenografted tumor growth." (PMID 35672728, 2022). "The knocking down or out EEF1D gene expression could enhance the sensitivity of ovarian cancer cells to DDP partially, which may be achieved via inactivating the PI3K/AKT signaling pathway, thus inducing cell apoptosis and decreasing repairment of DNA damage." (PMID 35672728, 2022). "In this study, we found that EEF1D is a key mediator of chemotherapy resistance to ovarian cancer." (PMID 35672728, 2022). "In this paper, we investigated the effects and mechanisms of increasing the sensitivity of ovarian cancer cells to cisplatin or cis-dichlorodiammine platinum (DDP) by knockdown and knockout of EEF1D gene in cellular and animal models." (PMID 35672728, 2022). "Compared with cells without KD or KO of EEF1D expression, the viabilities of ovarian cancer cells with EEF1D KD or KO were significantly decreased following DDP treatment (P < 0.05 or P < 0.01); the effect in SKOV3/DDP cells was more significant than that in SKOV3 cells." (PMID 35672728, 2022). "It was suggested that silencing the expression of EEF1D may inactivate the PI3K/Akt signaling pathway and regulate the balance of Bax/Bcl-2 to induce apoptosis, inhibit cell viability and reduce DNA damage repair in ovarian cancer cells." (PMID 35672728, 2022). "Furthermore, EEF1D overexpression cell lines should be constructed in future experiments to determine whether the overexpression of EEF1D increases Akt activation, and whether the PI3K/Akt inhibitors reverse the effect of EEF1D on increasing the resistance of ovarian cancer cells to cisplatin." (PMID 35672728, 2022).
ovarian clear cell adenocarcinoma (1 paper, 2016). A malignant glandular epithelial neoplasm characterized by the presence of clear and hobnail cells. "EEF1D strongly correlates with gene expression in ovarian clear cell adenocarcinomas." (PMID 26735889, 2016).
pancreatic cancer (1 paper, 2018). "In pancreatic cancer, the mRNA levels of EEF1A1, EEF1A2, EEF1B2, EEF1D and EEF1E1 were found to be significantly downregulated, as shown by Oncomine analysis." (PMID 29342219, 2018).
viral infections (1 paper, 2020). "Herein, the candidate genes PARP10, EXOSC4, GFUS and EEF1D, involved in various viral infections, were identified." (PMID 33255903, 2020).
tumor (11 papers, 2004 to 2023). "Compared with other groups, the EEF1D expression of the xenograft SKOV3/DDP tumor tissues in DDP treatment + EEF1D shRNA group was significantly reduced with Western blotting test." (PMID 35672728, 2022). "Compared with the DDP group, the tumor growth inhibition rate in the DDP treatment + EEF1D shRNA group was improved by ~ 50%." (PMID 35672728, 2022). "The TUNEL-positive cells of the xenograft tumor tissues in the DDP treatment + EEF1D shRNA group were significantly higher than those in the other groups (P < 0.01)." (PMID 35672728, 2022). "Interfering with EEF1D gene expression in mice xenografted tumor significantly affected the levels of OPTN, p-Akt, Bcl-2, Bax, cleaved caspase-3 and ERCC1 compared to DDP treated mice alone, and had less effect on PI3K, Akt and caspase-3." (PMID 35672728, 2022). "However TCGA analysis revealed that in addition to EEF1E1, mRNA levels of EEF1A2, EEF1G, and EEF1D are also significantly upregulated in tumor tissues." (PMID 29342219, 2018). "EEF1B2, EEF1G, EEF1D, EEF1E1 and EEF2, presented increased transcript levels in tumor group compared to normal, the most prominent being EEF1E1." (PMID 29342219, 2018). "According to our multiple pilot experiments, the SKOV3/DDP EEF1D KO cells do not form tumor in nude mice." (PMID 35672728, 2022). "In addition, the expression level of EEF1D, RBM38 and WDR43 ascended with higher tumor pathology grade (p-value = 0.019, 0.020, 0.034)." (PMID 34863153, 2021). "However, significant overexpression of EEF1A2, EEF1G, EEF1D, EEF1E1 and EEF2 was seen in tumor tissues." (PMID 29342219, 2018). "Therefore, blocking EEF1D could restrain EMT and PI3K/Akt activity resulting in the suppression of cell growth and tumor progression." (PMID 33029523, 2020).
cancer (8 papers, 2004 to 2022). A tumor composed of atypical neoplastic, often pleomorphic cells that invade other tissues. "Eukaryotic translation elongation factors 1 δ (EEF1D), has garnered much attention with regards to their role in the drug resistance of cancers." (PMID 35672728, 2022). "Overall, we see that in addition to EEF1A2; EEF1G, EEF1D, EEF1E1 and EEF2 are significantly upregulated in different cancer types and are associated with better and worse survival outcome in specific cancers." (PMID 29342219, 2018). "We also found that the previously reported pro-tumorigenic roles of EEF1G and EEF1D can be extended to other cancers viz." (PMID 29342219, 2018). "EEF1D levels were found to be upregulated in cancer tissue, in two analyses of Pyeon’s multi-cancer dataset." (PMID 29342219, 2018). "EEF1A1, EEF1A2 and EEF1D have previously been reported to be potential candidates for gene amplification, leading to observed overexpression in certain cancers." (PMID 29342219, 2018). "The present study indicated that restoring MAT1A and GNMT expression may suppress EEF1D expression that is potentially oncogenic in human cancer progression." (PMID 35008908, 2022). "Our study indicated that restoring MAT1A and GNMT expression may suppress EEF1D expression that is potentially oncogenic in human cancer progression." (PMID 35008908, 2022). "Therefore, previous studies regarding EEF1D have mainly focused on the relationship between EEF1D and cancers or tumors." (PMID 35672728, 2022). "Proteomic analysis shows that EEF1D is overexpressed in right-sided colon cancer and correlates with the invasive status of Adriamycin-resistant variants of DLKP, a squamous lung and cancer cell line." (PMID 33029523, 2020). "Accordingly, EEF1D is a potential target for cancer therapy." (PMID 29510727, 2018). "Likewise, increased levels of EEF1D transcript were observed in majority of datasets across multiple cancer types, however reduced levels were observed in seven datasets." (PMID 29342219, 2018). "Therefore, it was hypothesized that knocking down or removing the expression of the EEF1D gene may decrease drug resistance in cancer cells." (PMID 35672728, 2022). "EEF1D can activate the PI3K/Akt signaling pathway by activating small G proteins (Ras) to enhance cell repair and anti-apoptotic abilities to increase cancer cell resistance to drugs." (PMID 35672728, 2022). "The expression level of EEF1D, RBM38 and WDR43 ascended with the progression of cancer pathology grade." (PMID 34863153, 2021). "Higher expression of EEF1A2, EEF1B2, EEF1G, EEF1D, EEF1E1 and EEF2 was observed in most of the cancer types, whereas reverse trend was observed for EEF1A1." (PMID 29342219, 2018). "EEF1D can activate MAPK and/or PI3K/Akt signaling pathways by activating small G proteins (Ras) to enhance cell repair and anti-apoptotic capacity to increase drug resistance in cancer cells." (PMID 35672728, 2022). "In addition to EEF1A2, other translation factors EEF1B2, EEF1G, EEF1D, EEF1E1, and EEF2 were also found to be frequently overexpressed in different cancers." (PMID 29342219, 2018). "Keeping these lacunae in hindsight, we have undertaken a pan-cancer approach for comprehensive analysis of expression levels of seven elongation factors namely, EEF1A1, EEF1A2, EEF1B2, EEF1G, EEF1D, EEF1E1 and EEF2, using publicly available databases (Oncomine and TCGA)." (PMID 29342219, 2018).
neurodevelopmental disorder (4 papers, 2014 to 2023). A behavioral and cognitive disorder with onset during the developmental period that involves impaired or aberrant development of intellectual, motor, or social functions. "Mutations in the EEF1D gene have been identified as causes of several neurodevelopmental disorders." (PMID 38332912, 2023).
heart disease (1 paper, 2021). "The remaining proteins, i.e., EEF1D, TIMM13, and PMPCB, are involved in transferring aminoacyl-tRNAs, regulating heat-shock response, and maintaining mitochondrial functions, but their roles in heart disease contexts have not been investigated." (PMID 34211507, 2021).
psychiatric disorder (1 paper, 2018). A disorder characterized by behavioral and/or psychological abnormalities, often accompanied by physical symptoms. "Our study provides important insight for pathophysiology of psychiatric disorders, especially for patients carrying an EEF1D mutation." (PMID 30333725, 2018).
EEF1D also shares sentences with these, for which no sentence is quoted: oral squamous cell carcinoma (4 papers); infection (2); lymphoma (2); alcoholism (1); anaplastic large cell lymphoma (1); ankylosing spondylitis (1); astrocytoma (1); bladder cancers (1); Burkitt lymphoma (1); COVID-19 (1); Deep Venous Thrombosis (1); diffuse large B-cell lymphoma (1); esophageal cancer (1); follicular lymphoma (1); fragile X syndrome (1); head and neck carcinoma (1); Hodgkins lymphoma (1); ischemia (1); liver cancer (1); lymph node metastases (1); melanoma (1); microcephaly (1); myeloma (1); neuroblastoma (1); neurological diseases (1); non-small cell lung carcinoma (1); papillary renal cell carcinoma (1); schizophrenia (1); Sensory neuropathy (1); small cell lung carcinoma (1).
A further 1 disease shares a sentence with EEF1D in 1 paper.